ENSG00000259066 (novel protein)
Gene: Protein-coding gene on chromosome 14 (93,184,973 to 93,218,586, forward strand). Ensembl gene ENSG00000259066.
Genetic constraint (gnomAD): Loss-of-function variants: 9 observed, 20.06 expected, observed/expected ratio (o/e) 0.45, 90% interval 0.27 to 0.78. Missense variants: 130 observed, 188.57 expected, observed/expected ratio (o/e) 0.69, 90% interval 0.6 to 0.8. Synonymous variants: 60 observed, 66.31 expected, observed/expected ratio (o/e) 0.9, 90% interval 0.73 to 1.12.